ABCG1 (ATP binding cassette subfamily G member 1)
Diseases named in the same sentence as ABCG1 in open-access papers (continued):
Sharing a sentence is not in itself a finding about the gene and the disease.
lipid metabolism disorder (4 papers, 2017 to 2026). "The search for rare variants (gnomAD frequency less than 1 %) in the ABCA1, ABCG1, ABCG5, ABCG8 and NPC1L1 genes was performed using targeted sequencing data for 169 patients with lipid metabolism disorders." (PMID 42253452, 2026). "The aim of this work was to study the spectrum of rare variants in the cholesterol transporter genes ABCA1, ABCG1, ABCG5, ABCG8 and NPC1L1 that occur in patients with lipid metabolism disorders in the population of the Northwestern region of Russia." (PMID 42253452, 2026). "Ox-LDL can also downregulate ABCA1 and ABCG1 in THP-1 derived human macrophages resulting in lipid metabolism disorder in macrophages." (PMID 37021059, 2023). "Abnormal expression of ABCA1 and ABCG1 in the placenta can elicit lipid metabolism disorder and adverse pregnancy outcomes." (PMID 28630870, 2017). "et Zucc., can activate the activities of ABCA1, ABCG1, and ApoE with PGC-1α as the central target to inhibit lipid deposition in cells and improve lipid metabolism disorder in the kidney, thus preventing or delaying the occurrence and development of DN." (PMID 34485530, 2021).
lung fibrosis (4 papers, 2017 to 2023). "ABCG1 deficiency has been shown to promote lipid accumulation, proinflammatory macrophage activation, and pulmonary fibrosis." (PMID 36835058, 2023). "Therefore, our observations suggest that ABCG1 deficiency promotes pulmonary fibrosis by MWCNT, and this effect may be due to an increase in apoptosis and efferocytosis in BAL cells." (PMID 35008476, 2021). "Our results demonstrate that MWCNT instillation enhances pulmonary fibrosis in ABCG1 KO mice compared to wild-type controls." (PMID 35008476, 2021). "We demonstrated that MWCNT instillation increases apoptotic cells in BAL fluid and lung tissues of wild-type mice, and ABCG1 deficiency exacerbated apoptosis in BAL cells and promoted pulmonary fibrosis." (PMID 35008476, 2021). "Targeted deletion of the lipid efflux transporter, ATP-binding cassette sub-family G member 1 (Abcg1) increased foam cell formation and exacerbated lung fibrosis in mice from bleomycin challenge." (PMID 32549377, 2020). "Deletion of Abcg1 in mice exacerbates pulmonary fibrosis in response to bleomycin challenge." (PMID 36835058, 2023). "Mice lacking ABCG1 develop alveolar type II cell hypertrophy with lipid deposition, increased levels of surfactant, and develop more severe lung fibrosis after bleomycin." (PMID 28793908, 2017).
ovarian carcinoma (4 papers, 2021 to 2024). A malignant neoplasm originating from the surface ovarian epithelium. "Therefore, whether the ECM1a/ABCG1-mediated regulation of cholesterol levels in plasma or the tumor microenvironment can directly indicate a risk for or diagnosis of ovarian cancer requires more detailed investigation." (PMID 34244494, 2021). "Since we identified that ABCG1 can phosphorylate AKT2 in ovarian cancer, given the poor curative effects of ovarian cancer, the kinase role of ABCG1 may provide a therapeutic target for ovarian tumorigenesis after further investigations." (PMID 38896016, 2024). "Nevertheless, the results of our clinical analyses showed that ECM1a, integrin αXβ2, hnRNPLL, and ABCG1 were positively correlated with each other and that these molecules may be independent prognostic factors for poor survival in patients with ovarian cancer." (PMID 34244494, 2021). "Because many studies have reported that ABCG1 regulates intracellular cholesterol homeostasis mainly by affecting cholesterol efflux, we also tested the total cholesterol levels and cholesterol efflux in ovarian cancer cells overexpressing ECM1a, ECM1b, ABCG1, and hnRNPLL." (PMID 34244494, 2021).
pulmonary alveolar proteinosis (4 papers, 2017 to 2022). A rare lung disorder characterized by the filling of the pulmonary alveoli with proteinaceous material which stains positive with periodic acid-Schiff stain. "ABCG1 deficiency has been identified in patients with pulmonary alveolar proteinosis (PAP), a condition characterised by pulmonary surfactant accumulation." (PMID 28241820, 2017). "In keeping with this, ABCG1-deficient macrophages can also be found in patients with pulmonary alveolar proteinosis (PAP) – a rare disease characterized by the build-up of surfactant in the alveolar space – in conjunction with autoantibodies against GM-CSF blocking its signaling cascade." (PMID 31134013, 2019). "Interestingly, ABCG1 deficiency in human alveolar macrophages has been associated with pulmonary alveolar proteinosis (PAP), a rare condition characterised by accumulation of surfactant proteins and lipids in the alveolar space." (PMID 28241820, 2017). "Although not the topic of the present review, it is however important to mention here that ABCG1 plays a key role in maintaining lung lipid homeostasis and that impaired ABCG1 expression was reported in pulmonary alveolar proteinosis (PAP)." (PMID 28869506, 2017).
sarcoidosis (4 papers, 2019 to 2021). Sarcoidosis is a multisystemic disorder of unknown cause characterized by the formation of immune granulomas in involved organs. "Similarly, recognition of a deficiency of ATP-binding cassette (ABC) lipid transporter ABCG1 in sarcoidosis led us to study MWCNT instillation in myeloid-specific ABCG1 KO mice." (PMID 33918196, 2021). "Mice receiving rosiglitazone had lower MWCNT-induced pulmonary granulomas in association with a reduced pro-inflammatory response, and sustained ABCG1 expression in macrophages, supporting the concept that PPARγ deficiency could play a role in sarcoidosis pathogenesis." (PMID 32751786, 2020). "Additional studies demonstrated that cholesterol transporters ABCA1 and ABCG1 expressions were also altered in macrophages from patients with sarcoidosis." (PMID 32751786, 2020). "Whereas, down-regulation of PPAR-γ, and accordingly ABCA1 and ABCG1, in macrophages from sarcoidosis patients and mice imply a decrease in the efflux of HDL cholesterol from these macrophages." (PMID 31681260, 2019). "Alveolar macrophages from sarcoidosis patients and mice following MWCNT instillation show diminished expression of ABCG1 and ABCA1, and the deficiency of these transporters in MWCNT-instilled mice correlates with increased alveolar macrophage lipid accumulation." (PMID 31681260, 2019).
Stroke (4 papers, 2022 to 2025). Sudden impairment of blood flow to a part of the brain due to occlusion or rupture of an artery to the brain. "A major cell type in arteries that accumulates cholesterol is macrophages, and it is thought that increasing ABCA1/ABCG1 expression specifically in macrophages within arteries may protect against heart disease and stroke." (PMID 40906448, 2025). "Two transporters, ABCA1 and ABCG1, may protect against heart disease and stroke by removing excess cholesterol from artery cells." (PMID 40906448, 2025).
Alzheimer disease (3 papers, 2015 to 2024). A progressive, neurodegenerative disease characterized by loss of function and death of nerve cells in several areas of the brain leading to loss of cognitive function such as memory and language. "Furthermore, ABCG1 has been reported to be associated with a risk for Alzheimer’s disease." (PMID 27196068, 2016). "However, the data on the clinical relevance of ABCG1 in Alzheimer’s disease are conflicting and require further studies." (PMID 39857239, 2024). "In hypothesis-driven tests, there was significant association between general cognitive function and four genes previously associated with Alzheimer's disease: TOMM40, APOE, ABCG1 and MEF2C." (PMID 25644384, 2015). "A possible link between ABCG1 and Alzheimer’s disease may be through its effects on lipid metabolism in the brain, as clinical studies show that ABCG1 is involved in impairing the cholesterol efflux capacity in cerebrospinal fluid in patients with Alzheimer’s disease." (PMID 39857239, 2024). "ABCG1 is expressed in both neurons and astrocytes, whereas ABCG4 has been detected in neurons and astrocytes, as well as microglia from patients with Alzheimer’s disease." (PMID 27196068, 2016). "In this study, we examined the effects of ABCG1 and ABCG4 on amyloid precursor protein (APP) processing, the product of which, amyloid β (Aβ), is involved in the pathogenesis of Alzheimer’s disease." (PMID 27196068, 2016). "If this is the case, studies using neurons are essential to understand the effects of ABCG1 on APP processing and Aβ secretion in the CNS and to reveal the relationship between the expression of ABCG1 and Alzheimer’s disease." (PMID 27196068, 2016). "ABCG1 and ABCG4 may play important roles in suppression of Aβ generation and pathogenesis of Alzheimer’s disease." (PMID 27196068, 2016). "ABCG1 and ABCG4 may inhibit the development of Alzheimer’s disease and can be targets for the treatment of Alzheimer’s disease." (PMID 27196068, 2016). "ABCG1 and ABCG4 could be new targets for prevention and treatment of Alzheimer’s disease." (PMID 27196068, 2016).
diabetic nephropathy (3 papers, 2014 to 2025). "We have investigated the role of cellular cholesterol transport proteins including adenosine triphosphate binding cassette transporter A1 (ABCA1), G1 (ABCG1) and scavenger receptor class B type I (SR-BI) in diabetic nephropathy." (PMID 25181357, 2014). "Our study has provided new data on ABCG1 and SR-BI in diabetic nephropathy." (PMID 25181357, 2014). "The role of ABCG1 and SR-BI in renal cellular cholesterol efflux in diabetic nephropathy has not been determined." (PMID 25181357, 2014).
heart failure (3 papers, 2016 to 2023). Inability of the heart to pump blood at an adequate rate to meet tissue metabolic requirements. "We found hypomethylation of ABCG1 in whole blood was associated with the risk of CHD in both studies, which was enhanced in heart failure (HF) patients, female and younger subjects." (PMID 37507725, 2023). "Subsequently, we assessed the link between ABCG1 methylation and the condition of heart failure (HF)." (PMID 37507725, 2023).
Hepatic steatosis (3 papers, 2017 to 2025). Steatosis is a term used to denote lipid accumulation within hepatocytes. "Unfortunately, ABCA1 and ABCG1 are downstream genes of LXR, activation of which can lead severe hepatic steatosis." (PMID 31938053, 2020). "Although no study aimed to investigate the contribution of Abcg1 in non-alcoholic steatohepatitis (NASH) and more widely in fatty liver diseases (NAFLD) has been conducted, several lines of evidence indicate that Abcg1 plays an important role in lipid homeostasis in the liver." (PMID 28869506, 2017).
lung adenocarcinoma (3 papers, 2020 to 2023). A carcinoma that arises from the lung and is characterized by the presence of malignant glandular epithelial cells. "In lung adenocarcinomas, ABCG1 could have chemoresistance-related properties, and the depletion of ABCG1 increased the disease’s susceptibility to cisplatin therapy." (PMID 36650399, 2023).
neuroblastoma (3 papers, 2014 to 2019). Neuroblastoma (NB) is the most common solid, extracranial childhood tumor. "Next, we examined the distribution of endogenously expressed ABCG1 in neuroblastoma SH-SY5Y cells." (PMID 25302608, 2014). "Although hypoxia-inducible erythropoietin (EPO) gene expression was shown in human neuroblastoma cells, downregulation of Epo mRNA was found in LuM1 aggregates as compared with Colon26 cells, We next examined whether ABCG1 depletion altered HIF-1α levels in tumors." (PMID 30364132, 2018).
preeclampsia (3 papers, 2018 to 2025). Preeclampsia is a hypertensive disorder of pregnancy that is characterized by new-onset hypertension with proteinuria presenting after 20 weeks of gestation, and depending on mild or severe forms may initially present with severe headache, visual disturbances, and hyperreflexia. "Therefore, both ABCA1 and ABCG1 are important to protect against toxic effects of oxysterols on placental and fetal development and placental function, thereby reducing the risks associated with pregnancy complications such as preeclampsia." (PMID 34829614, 2021). "In EVT, preeclampsia induced pronounced changes in cholesterol transporter expression: ABCG1 was significantly downregulated (95th percentile CPM: Ctrl = 335.2; PE = 146.0, p = 3.60e-07), while ABCA1 showed a trend toward upregulation (95th percentile CPM: Ctrl = 261.4; PE = 528.2, p = 0.11)." (PMID 41446579, 2025). "In humans, fetal IUGR and maternal preeclampsia decrease Abca1 and Abcg1 expression." (PMID 29896121, 2018).
retinal degeneration (3 papers, 2019 to 2024). Degeneration of the retina. "Targeting the deletion of cholesterol efflux genes, such as Abca1 and Abcg1, promoted the formation of drusen-like lesions and finally resulted in retinal degeneration with age, which seems to support the hypothesis that drusen cause AMD." (PMID 38731137, 2024). "A mouse model lacking ABCA1 and ABCG1 showed lipid accumulation, retinal degeneration, and inflammation." (PMID 37587376, 2024).
type 1 diabetes (3 papers, 2013 to 2023). "Cholesterol efflux from J774A.1 macrophages to glycated lipid-free apoA-I via ABCA1 or glycated drHDL via an ABCG1-dependent mechanism was unaltered, as was efflux to minimally modified apoA-I from people with Type 1 diabetes, or controls." (PMID 23741493, 2013).
dementia (2 papers, 2015 to 2023). Loss of intellectual abilities interfering with an individual's social and occupational functions. "We observed association of general cognitive function with four genes previously associated with AD or neuropathological features of AD and related dementias (TOMM40, APOE, MEF2C and ABCG1)." (PMID 25644384, 2015).
depression (2 papers, 2023 to 2025). "Genes associated with depression or neuro-diseases were found in this study, such as ABCG1, ASMTL, CACNA1F, COX7A1, GRID2, HTR3E, and SHANK2." (PMID 37766304, 2023).
gastric cancer (2 papers, 2014 to 2025). A primary or metastatic malignant neoplasm involving the stomach. "In the present study, we found three members of MDR related ABC transporters (ABCB1, ABCC5 and ABCG1)were targeted by miR-129-5p, which was a hyper-methylated miRNA in gastric cancer MDR cell lines." (PMID 25344911, 2014). "Once the miR-129-5p were hyper-methylated and silenced in gastric cancer cells, the expression of MDR related ABC transporters (ABCB1, ABCC5 and ABCG1) would increase and directly lead to a MDR phenotype." (PMID 25344911, 2014). "In conclusion, the present study demonstrated that miR-129-5p plays an important role in antagonizing MDR in gastric cancer cell lines by directly targeting and inhibiting three MDR-related ABC transporters--ABCB1, ABCC5 and ABCG1." (PMID 25344911, 2014).
head and neck squamous cell carcinoma (2 papers, 2018 to 2021). A squamous cell carcinoma that arises from any of the following anatomic sites: lip and oral cavity, nasal cavity, paranasal sinuses, pharynx, larynx, and salivary glands. "Analyzing PrognoScan database indicated that elevated expression of ABCG1 and ABCG2 were correlated with poor prognosis of patients suffering from colorectal cancer and head and neck squamous cell carcinoma." (PMID 30364132, 2018).
hypertriglyceridemia (2 papers, 2017 to 2021). A laboratory test result indicating elevated triglyceride concentration in the blood. "A previous in vitro study has demonstrated a reduction in macrophage ABCG1 expression when higher triglyceride levels were present in the culture medium, indicating that hypertriglyceridemia can contribute to macrophage reverse cholesterol transport reduction in the vascular wall." (PMID 34837967, 2021). "However the absence of association between the two SNPs and TG levels observed in REGRESS (plasma TG levels < 3.5 g/L) suggests that modulation of LPL activity by ABCG1 might only alter circulating TG concentrations in subjects exhibiting fasting or postprandial hypertriglyceridemia." (PMID 28869506, 2017).
lipidosis (2 papers, 2017 to 2024). "It was indeed reported that both Abca1 -/- and Abcg1-/- mice accumulate lipids into T2P cells exhibit an age-related progressive pulmonary disease, including lipidosis and chronic inflammation." (PMID 38970705, 2024). "However, the timeline of events was less clear in a separate study, which also reported inflammatory cytokine, neutrophil and lymphocyte infiltration alongside lipidosis in the lungs of Abcg1−/− mice." (PMID 28241820, 2017). "Wojcik and coauthors proposed that one of two mechanisms could be occurring: i) lipid accumulation causes inflammation or ii) absence of Abcg1 triggers inflammation that subsequently leads to the observed lipidosis; which one of these events predominates is still unclear." (PMID 28241820, 2017).
liver fibrosis (2 papers, 2021 to 2023). "Importantly, increased cholesterol accumulation in HSCs accelerates liver fibrosis, and thus enhanced efflux through ABCA1 and ABCG1 induction while reducing ACAT2 may be additional mechanisms by which Aramchol reduces HSC fibrogenesis." (PMID 34151243, 2021).
lung disease (2 papers, 2024). "Thus, ABCG1 plays an important biological role in lung function, but despite similar data suggesting the potential involvement of ABCG1 in the pathogenesis of lung disease in experimental animal models, the data on the clinical significance of ABCG1 are still scarce." (PMID 39857239, 2024).
Nephropathy (2 papers, 2011 to 2014). A nonspecific term referring to disease or damage of the kidneys. "Protein expressions of ABCA1, ABCG1 and SR-BI were significantly reduced in the kidneys from diabetic animals with the greatest reduction seen in mice with nephropathy." (PMID 25181357, 2014). "Histological examination revealed that ABCA1, ABCG1 and SR-BI were mainly expressed in renal tubules, and there was a marked reduction in all three cholesterol transporters in diabetic mice especially in the group with nephropathy." (PMID 25181357, 2014). "In conclusion, the expression of ABCA1, ABCG1 and SR-BI in mesangial cells and tubular cells were significantly decreased under hyperglycemic conditions in vitro, and renal expression of these cholesterol transporters was reduced in diabetic mice with nephropathy." (PMID 25181357, 2014).
non-small cell lung carcinoma (2 papers, 2023 to 2025). A group of at least three distinct histological types of lung cancer, including non-small cell squamous cell carcinoma, adenocarcinoma, and large cell carcinoma. "Single-nucleotide polymorphisms (SNPs) of ABCG1 in the first cytoplasmic domain (within intron 2) are associated with survival of patients with non-small-cell lung cancer." (PMID 36765727, 2023).
pancreatic cancer (2 papers, 2015 to 2020). "We also compared the expression of LXRβ and known target genes SREBF1, ABCA1, ABCG1, FASN, and SCD in pancreatic cancer tissue to normal pancreas tissue and found that transcript levels of LXRβ and its target genes are elevated in the tumor tissues." (PMID 33348693, 2020).
pneumonia (2 papers, 2020 to 2023). An acute, acute and chronic, or chronic inflammation focally or diffusely affecting the lung parenchyma, caused by an infection in one or both of the lungs (by bacteria, viruses, fungi, or mycoplasma.). "In the present study, we found that the SPA+ABCG1+ subset was enriched in the S/TB region with elevated expression of the ECM1-α6β4-ABCG1 axis in lung tissues from patients with pneumonia." (PMID 32157214, 2020). "Finally, we found that SPA+ABCG1+ cells and molecules in the ECM1-α6β4-ABCG1 axis were enriched in the S/TB region of lung tissue samples from patients with pneumonia." (PMID 32157214, 2020). "Importantly, Sca-1+Abcg1+ and SPA+ABCG1+ cells specifically existed in the small bronchioles of Gprc5a-KO mice and patients with pneumonia, respectively." (PMID 32157214, 2020).